LEP (leptin)
Diseases named in the same sentence as LEP in open-access papers (continued):
Sharing a sentence is not in itself a finding about the gene and the disease.
Insulin resistance (continued). "Leptin resistance can occur either as a defect in blood-brain barrier leptin transport, or through intracellular mechanisms that are similar to insulin resistance." (PMID 30373146, 2018). "Genetic ablation or pharmacologic inhibition of neuronal RAP1A gene in mice reduces insulin resistance, improves leptin sensitivity in the hypothalamus and protects from dietary obesity." (PMID 30573851, 2018). "Higher circulating leptin levels lead to leptin resistance which in turn leads to greater insulin resistance." (PMID 29743077, 2018). "The leptin-to-adiponectin ratio, as another measure of systemic insulin resistance, was elevated in 30-week-old B6-Tg(Ifi202b) mice and confirmed the impaired insulin sensitivity." (PMID 29478099, 2018). "Evidence surrounding the relationship between leptin and insulin resistance is controversial, but it is thought that plasma leptin concentrations are positively correlated with insulin resistance." (PMID 29601521, 2018). "High leptin concentrations, chronic low-grade inflammatory status, and insulin resistance often coexist in metabolically unhealthy obese subjects, who are at higher risk of developing type 2 diabetes." (PMID 28640843, 2017). "This study evaluated some probable predictors of metabolic syndrome (MS), such as leptin and adiponectin concentrations, the leptin/adiponectin ratio, insulin resistance, and adiposity, in a sample of child survivors of lymphoma and leukemia in Mexico City." (PMID 28193268, 2017). "Further studies comprising subjects with different glycemic status will be necessary to determine the cutoff points for insulin resistance based on plasma leptin and adiponectin levels." (PMID 28626772, 2017). "CVD risk factors (central obesity, insulin resistance, and dyslipidemia) are associated with decreased ADIPO and increased leptin levels." (PMID 28947858, 2017). "Hypertrophic adipocytes are characterized by releasing high amounts of leptin, pro-inflammatory cytokines, low adiponectin, and insulin-resistance." (PMID 28513533, 2017). "Data collected concerned the body mass index, waist circumference, systolic blood pressure, diastolic blood pressure, fasting blood glucose, plasma lipids, adiponectin, leptin, insulin and homeostasis model for assessment of insulin resistance (HOMA-IR)." (PMID 28878827, 2017). "Other studies demonstrated that insulin resistance is most closely correlated with the leptin levels." (PMID 29088261, 2017). "Fasting leptin concentrations of ≥15 ng/mL have been described as the cutoff value to predict insulin resistance." (PMID 28222742, 2017). "Adiponectin plays an important role in protecting against insulin resistance and inflammation, whereas leptin and resistin have the opposite effects." (PMID 28448547, 2017). "Leptin and adiponectin, both of which are adipocyte-derived hormones, significantly contribute to the relationship between hot flashes and subclinical insulin resistance." (PMID 28448547, 2017). "In other studies that include individuals with insulin-resistance/metabolic syndrome, leptin-to-adiponectin ratio and the prevalence of metabolic syndrome was significantly lower in subjects treated with BC." (PMID 28704936, 2017). "In the present study, we found an association between hot flash-associated insulin resistance as measured by HOMA-IR and leptin-to-adiponectin ratio in postmenopausal women." (PMID 28448547, 2017). "In aggregate, these studies shed light on hypothalamic inflammation as an important modulator of energy homeostasis, which sustains leptin and insulin resistance and promotes obesity." (PMID 28835706, 2017). "Overall, HFD resulted in increased caloric intake, insulin resistance, impaired glucose tolerance and higher circulating levels of leptin, while PNS increased the leptin/adiponectin ratio, an index of metabolic risk in adult male subjects." (PMID 28706476, 2017).
Insulin resistance (continued). "The serum levels of various adipokines, including leptin and adiponectin, have been indicated as biomarkers for insulin resistance and metabolic syndrome." (PMID 28178355, 2017). "Surprisingly, however, high plasma leptin levels often coexist with insulin resistance in human subjects." (PMID 28609470, 2017). "As it is known, the plasma concentration of the receptor in question is one of the factors influencing the level of insulin resistance and leptin resistance." (PMID 28758947, 2017). "On the other hand, patients with congenital generalized lipodystrophy, a rare genetic disorder characterized by extreme leanness and very low levels of circulating leptin, display high-insulin resistance and premature diabetes." (PMID 28626772, 2017). "While, the majority of subjects were obese or over weight hence one explanation for our result is “irisin resistance” in obese people as same as leptin and insulin resistance." (PMID 28497081, 2017). "Leptin and adiponectin have opposite effects on subclinical inflammation and insulin resistance, both involved in the development of metabolic syndrome (MS)." (PMID 29020116, 2017). "According to literature, high plasma levels of leptin are related to insulin resistance, and leptin reduces insulin sensitivity in isolated adipocytes." (PMID 28830524, 2017). "The adiponectin/leptin ratio has been reported to correlate with insulin resistance more closely than adiponectin or leptin alone or even HOMA13." (PMID 28747790, 2017). "In 2008-2010, leptin, the homeostasis model assessment of insulin resistance (HOMA-IR) and C-reactive protein (CRP) were measured." (PMID 28400989, 2017). "With longer administration, BTS improved insulin resistance, and subsequently reduced serum levels of leptin and triglyceride in parallel with decreased visceral white adipose tissue volume and adipocyte size." (PMID 28360931, 2017). "Increased leptin levels, probably reflecting leptin resistance, were strongly related to insulin resistance." (PMID 28369078, 2017). "We examined the associations of leptin, hs (high sensitivity)- CRP and insulin resistance with bone turnover markers (BTMs) and bone characteristics in 55 young obese adults (median BMI 40 kg/m2) and 65 non-obese controls." (PMID 28640843, 2017). "We also show that depot-selective adipose hyperplasia is discordant with suppressed leptin levels and impaired insulin-mediated suppression of lipolysis in severely affected patients, while insulin resistance is seen in all." (PMID 28414270, 2017). "Twenty-five days’ treatment lowered serum glucose, insulin, leptin, and triglycerides, and reduced homeostasis model assessment-insulin resistance." (PMID 28360931, 2017). "Remarkably, exogenous leptin administration greatly ameliorates metabolic dysfunctions, oxidative damage, insulin resistance and over-weight in ob/ob mice." (PMID 29206172, 2017). "It elevated the plasma levels of insulin, insulin resistance and leptin but decreased the levels of adiponectin, BMC and BMD." (PMID 29176994, 2017). "We assessed leptin, adiponectin, and homeostatic model assessment of insulin resistance (HOMA-IR) in mid-childhood." (PMID 27586368, 2017). "This ancillary cross-sectional analysis shows that leptin concentrations negatively correlated with ucOC and positively correlated with insulin resistance and β-cell function estimates in healthy children." (PMID 28286536, 2017). "In fact, low adiponectin and high leptin concentrations are observed in children with MS and insulin resistance." (PMID 28193268, 2017). "It is well described that proinflammatory cytokine tumour necrosis factor α (TNFα) and the adipocytokine adiponectin and leptin play crucial roles in insulin resistance." (PMID 29104874, 2017). "Similar results were obtained from patients with severe lipodystrophy in which chronic leptin treatment improved hepatic and peripheral insulin resistance." (PMID 28786989, 2017).
Insulin resistance (continued). "It was reported that systematic infusion of leptin reversed insulin resistance in congenital lipodystrophic mice characterized by hyperinsulinemia and hyperglycemia." (PMID 28786989, 2017). "We also evaluated leptin and adiponectin ratio since it has been believed to be a better determinant of insulin resistance and metabolic complications than either leptin or adiponectin alone." (PMID 29295491, 2017). "Significantly increased serum leptin and insulin concentrations and impaired insulin tolerance in the male offspring of dams treated with 2.0 mg/kg body weight of Cd and Hg suggested insulin resistance." (PMID 27814245, 2017). "Homeostatic model assessment (HOMA) was used to assess beta cell function (HOMA1-β and HOMA2-β) and insulin resistance (HOMA1-IR and HOMA2-IR).The relationships between glycemic traits and 12 LEP variants were determined." (PMID 29255202, 2017). "The most popularly cited mechanisms are the impact of leptin, thyroid hormones resistance, mitochondrial dysfunction, changes in the activity of deiodinases, chronic low-grade inflammation, and insulin resistance." (PMID 29244733, 2017). "The adipocyte-derived hormones leptin, adiponectin, and resistin are known to play an important role in the development of insulin resistance, the main pathologic mechanism of many metabolic and vascular diseases." (PMID 28448547, 2017). "In abdominal obesity, visceral adipocytes produce several adipocytokines, such as adiponectin, resistin, and leptin, which increase insulin resistance." (PMID 28775758, 2017). "In contrast, the same treatment with corn oil had a positive impact only on triglycerides, leptin, adiponectin and insulin resistance." (PMID 29165388, 2017). "In hepatocytes, janus kinase 2/signal transducer and activator of transcription 3 pathway is the main pathway of its action, and leptin is involved in hepatic steatosis and insulin resistance through suppressor of cytokine signaling expression." (PMID 28081181, 2017). "Third, further investigation is needed to evaluate the relationships between adiponectin and other markers of insulin resistance, for example, leptin." (PMID 28654680, 2017). "Two markers novel to this current report, increases of leptin (satiety hormone) and afamin (related to albumin), likely also reflect metabolic disturbances by corticosteroids, possibly downstream of insulin resistance." (PMID 27530235, 2016). "We performed analyses of fat mass, fat free mass, plasma (p)-glucose, p-insulin, Homa-Index (a measure of insulin resistance), serum (s)-leptin, s-ghrelin and of the hypothalamic volume in scans obtained by magnetic resonance imaging (MRI) at 3 Tesla." (PMID 26824435, 2016). "A number of these adipokines, such as adiponectin, leptin, TNF-α, resistin, PAI-1, IL-6 and MCP-1, were found to be directly related to insulin resistance and associated morbidities." (PMID 27651836, 2016). "Lipodystrophy is a syndrome characterized by adipose tissue deficiency; this results in ectopic lipid accumulation in organs and causes non-alcoholic fatty liver disease (NAFLD), reduced blood leptin insulin resistance and T2D." (PMID 27483259, 2016). "In females, MS180 decreases insulin resistance biomarkers in chow-fed rats, but affects the response to an obesogenic diet later in life, and alters leptin mRNA levels." (PMID 27611197, 2016). "Physical activity has been associated with lower levels of total cholesterol, triglycerides, leptin, and improved glycemic control and reduced insulin resistance in pregnant women." (PMID 27485519, 2016). "Six leptin‐correlating proteins are part of the ten‐protein inflammation panel, which confirms the connection between insulin resistance and inflammation." (PMID 28007936, 2016).
Insulin resistance (continued). "In particular, F-FOPS mice exhibited substantial increases in cecal propionate production, which were significantly correlated with reductions in fasting glucose and insulin levels, the index of insulin resistance, and plasma leptin levels." (PMID 26731528, 2016). "Plasma leptin levels correlated with plasma fasting insulin levels, pre-pregnant body mass index, homeostasis model assessment-insulin resistance and quantitative insulin sensitivity check index both in GDM and NGT group (P < 0.05)." (PMID 27034205, 2016). "The adipokines including leptin, adiponectin, visfatin and resistin have a role in insulin resistance in obese subjects and there is a significant relation between insulin resistance and obesity." (PMID 27891497, 2016). "Leptin and insulin resistance are pathophysiological mechanisms that need to be further elucidated, along with the roles of the immune system and neurotropic factors." (PMID 26978741, 2016). "Data were collected on waist circumference (WC), body mass index (BMI), waist-to-hip ratio (WHR), body fat (BF%), fasting blood glucose, plasma lipids, adiponectin, leptin, insulin and homeostasis model for assessment of insulin resistance (HOMA-IR)." (PMID 27189377, 2016). "Together, these findings suggest that leptin levels reflect nutritional status and insulin resistance in hospitalized cirrhotic patients." (PMID 27583675, 2016). "Circadian rhythm disruption adversely affects the metabolic responses to feeding (partly due to insulin resistance), alters leptin secretion patterns favoring energy intake, and leads to dysregulated innate immunity and systemic inflammation." (PMID 26867201, 2016). "SOCS3 is a major negative regulator of insulin and leptin signaling and is thought to contribute to the pathogenesis of insulin resistance." (PMID 27337171, 2016). "Being overweight is a recognized condition of insulin resistance commonly accompanied by resistance to leptin." (PMID 27598982, 2016). "This study shows that long-term SF exposure (4 weeks) during the sleep period in mice leads to increased visceral fat mass, VWAT inflammation, as wells as systemic insulin resistance and increased leptin plasma levels." (PMID 27739530, 2016). "Glucose, insulin, adiponectin, leptin, and insulin resistance (IR) index were measured on days 1 and 12 after the onset of MI." (PMID 26989445, 2016). "As adiponectin and leptin can reverse insulin resistance, the serum levels of adiponectin and leptin were measured." (PMID 27088095, 2016). "Our measurements of the serum leptin level and calculations of the insulin resistance index, as well as insulin tolerance test also suggested that our diabetic gerbils exhibited insulin resistance and leptin resistance." (PMID 27427908, 2016). "This protein mediates fatty acid induced inflammation and leads to leptin and insulin resistance in the central nervous system." (PMID 27623010, 2016). "For instance, leptin resistance can lead to the inhibition of insulin signaling, while insulin resistance can alter leptin signaling in a hypothalamic cell line." (PMID 27812350, 2016). "In the present study, the authors aimed to show the effects of the reduction mammaplasty on serum leptin levels and insulin resistance." (PMID 26550014, 2015). "Administration of a leptin antagonist in newborn rats promoted overweight and leptin/insulin resistance as well as changes in hypothalamic miRNA expression profile in adulthood." (PMID 25729348, 2015). "In hibernating animals, the adiponectin suppression and increased leptin secretion are coordinated to induce insulin resistance and decreased appetite in response to decreased food availability." (PMID 25991926, 2015). "Increased plasma LEP levels correlated with final larger infarction volume and leptin was evaluated as harmful in IS development, potentiated by insulin resistance." (PMID 26783391, 2015). "The addition of leptin adds biological plausibility to our findings in relation to insulin resistance." (PMID 26368559, 2015).
Insulin resistance (continued). "Our previous study showed that CSX subjects had decreased serum adiponectin but higher leptin and insulin resistance (IR)." (PMID 26413164, 2015). "In in vivo studies, intermittent hypoxia has been found to induce insulin resistance in mice, and this is accompanied by an up-regulation of leptin gene expression in adipose tissue." (PMID 25573199, 2015). "In other studies, leptin has been shown to regulate glucose homoeostasis by reversing lipid accumulation and beneficially affecting the insulin resistance and the cell function." (PMID 26448786, 2015). "Although leptin activates some carcinogenic pathways, adiponectin appears to have a regulatory role in insulin resistance and to exert antineoplastic activities and interfere with leptin-induced processes (Balsan, Vieira, Oliveira, & Portal, 2015)." (PMID 26251693, 2015). "Furthermore, modulation of adipocytokines serum concentration (i.e., elevated plasma adiponectin and decreased plasma leptin) may also underlie the improvement of insulin resistance and could be a possible mechanism for the beneficial cardiovascular effects of metformin and sitagliptin." (PMID 25838947, 2015). "Central leptin and insulin resistance, hallmarks of disrupted nutrient/energy sensing by the hypothalamus, are common mechanisms for weight gain caused by aging and diet." (PMID 26236282, 2015). "Mice fed a HFD gained significant fat mass and displayed increased leptin levels, increasing insulin resistance (poor HOMA-IR) and worse glucose tolerance test (GTT) performance in comparison to mice fed a LFD, as expected." (PMID 25633992, 2015). "Other investigators demonstrated that the dietary curcumin supplement improved insulin resistance and hyperglycemia in diabetic mice with a simultaneous increase in plasma leptin and insulin levels." (PMID 25901155, 2015). "Serum adiponectin, leptin, F2-isoprostane, insulin, and lipid profile were estimated, and homeostatic model assessment of insulin resistance computed." (PMID 26273674, 2015). "MetS rats exhibited increased body weight, central adiposity, hypertension, insulin resistance, and elevated circulating levels of adiponectin and leptin." (PMID 26609312, 2015). "Evidence from exercise trials in men and women at risk of either breast or colon cancer suggests that physical activity, at levels recommended for cancer prevention, can reduce adiposity, leptin, some inflammatory markers and insulin resistance." (PMID 25706622, 2015). "It has been shown that adipose tissue plays an important role in regulating lipid homeostasis by secretion of adipokines, like adiponectin and leptin, and is involved in hepatic steatosis and insulin resistance." (PMID 26690553, 2015). "Increased plasma levels of insulin and leptin denoted insulin resistance and leptin resistance in HF-DIO mice." (PMID 26633898, 2015). "To investigate the effect of RBP on the regulatory mechanism of hyperglycemia and insulin resistance in more detail, we examined the levels of the two major blood glucose and lipid regulating adipokines, adiponectin and leptin, in the plasma of HCHF-fed rats." (PMID 26247962, 2015). "More information needs to be obtained by comparing insulin resistance to leptin levels during long-term follow-up after treatment." (PMID 25821463, 2015). "The differences in leptin signaling pathways in the central nervous system were considered to be based on a sex-specific relationship between leptin and insulin resistance." (PMID 26783391, 2015). "In a number of studies, it has been shown that an elevated leptin level potentiated insulin resistance and arterial hypertension and activated proinflammatory factors while adiponectin, on the contrary, possessed cardioprotective effects." (PMID 26504811, 2015). "It has been shown that overexpression of TFAP2B results in lipid accumulation by enhancing glucose transport and inducing insulin resistance and decreases the secretion of adiponectine and leptin in human adypocites." (PMID 25890290, 2015).